SYCP2 (synaptonemal complex protein 2)
Description:
Major component of the axial/lateral elements of synaptonemal complexes (SCS) during meiotic prophase. Plays a role in the assembly of synaptonemal complexes. Required for normal meiotic chromosome synapsis during oocyte and spermatocyte development and for normal male and female fertility. Required for insertion of SYCP3 into synaptonemal complexes. May be involved in the organization of chromatin by temporarily binding to DNA scaffold attachment regions. Requires SYCP3, but not SYCP1, in order to be incorporated into the axial/lateral elements.
Synonyms: SCP-2; SCP2; SPGF1
Tractability: PROTAC: ubiquitination databases record sites on it.
Gene: Protein-coding gene on chromosome 20 (59,863,564 to 59,933,655, reverse strand). Ensembl gene ENSG00000196074.
Subcellular location: Nucleus; Chromosome
Subcellular location (Human Protein Atlas): Nucleoplasm
Pathways (Reactome):
Reproduction: Meiotic synapsis
Gene Ontology:
Molecular function: DNA binding
Biological process: homologous chromosome pairing at meiosis; homologous recombination; reciprocal meiotic recombination; synaptonemal complex assembly
Cellular component: condensed chromosome, centromeric region; condensed nuclear chromosome; lateral element; nucleus; synaptonemal complex; chromosome
Genetic constraint (gnomAD): Loss-of-function variants: 20 observed, 79.51 expected, observed/expected ratio (o/e) 0.25, 90% interval 0.18 to 0.37. The upper end of that interval is the gene's LOEUF score, 0.37, which puts it in group 1 of 6, group 1 being the genes least tolerant of losing a copy. Missense variants: 864 observed, 874.66 expected, observed/expected ratio (o/e) 0.99, 90% interval 0.93 to 1.04. Synonymous variants: 295 observed, 305.73 expected, observed/expected ratio (o/e) 0.96, 90% interval 0.88 to 1.06.
Homologues: Orthologues: chimpanzee SYCP2 (98% identical), macaque SYCP2 (95% identical), pig SYCP2 (71% identical), rabbit SYCP2 (69% identical), dog SYCP2 (66% identical), mouse Sycp2 (63% identical), rat Sycp2 (61% identical), tropical clawed frog sycp2 (29% identical), zebrafish sycp2 (12% identical), guinea pig Sycp2 (10% identical). Paralogues in human: SYCP2L (15% identical).
Diseases named in the same sentence as SYCP2 in open-access papers:
SYCP2 is named in the same sentence as 36 diseases in open-access papers, as found by Europe PMC text mining. Sharing a sentence is not in itself a finding about the gene and the disease. The quoted sentences say what the papers report.
breast carcinoma (7 papers, 2018 to 2025). "Previously, we observed that SYCP2 is significantly overexpressed specifically in ovarian and breast cancer patients, where its elevated levels are strongly associated with poorer clinical outcomes and prognosis." (PMID 40918650, 2025). "GO, KEGG, GSEA, and GSVA were performed to investigate the underlying functions and mechanisms of SYCP2 in breast carcinoma in depth." (PMID 36159998, 2022). "Furthermore, the clinical data of 1,095 breast cancer patients in the TCGA database confirms that high SYCP2 expression is associated with poor prognosis." (PMID 38383600, 2024). "Moreover, the ROC curves suggested the significant diagnostic ability of SYCP2 for breast carcinoma." (PMID 36159998, 2022). "Moreover, ROC curves suggested the significant diagnostic ability of SYCP2 for breast carcinoma, and as time went on, SYCP2 had more accurate prognostic efficacy." (PMID 36159998, 2022). "Given that SYCP2 has been reported as aberrantly expressed in ovarian and breast cancers—where its overexpression is associated with resistance to therapies targeting the DNA damage response —it is plausible that SYCP2L may exhibit similar aberrant activation in the context of ASCC." (PMID 40559621, 2025). "We found that DNA hypomethylation at two sites near the SYCP2 promoter strongly correlated with high SYCP2 expression in 309 breast cancer samples." (PMID 38383600, 2024). "Here, we show that SYCP2 expression is aberrantly upregulated in breast cancer, ovarian cancer, and certain other cancer types." (PMID 38383600, 2024). "Given the level of ER varies in breast cancer patients, we analyzed the correlation between the status of ER levels with SYCP2 expression and the outcome of hormone treatment (Tamoxifen) with SYCP2 expression." (PMID 38383600, 2024). "From IHC staining, we classified patients into SYCP2low and SYCP2high groups based on the amount of positive staining and intensity of SYCP2 using a similar method as in the analysis of breast cancer samples." (PMID 38383600, 2024). "To further examine the expression of SYCP2 in cancer, we stained SYCP2 by IHC in tumor samples from breast cancer patients." (PMID 38383600, 2024). "In this study, bioinformatics analysis was conducted on the expression levels and prognostic value of SYCP2 in breast carcinoma with the use of high-throughput transcriptomic data that originated from TCGA/GEO." (PMID 36159998, 2022). "It was confirmed that SYCP2 is significantly upregulated in breast carcinoma tissues as compared with normal samples, and patients with high-SYCP2 expression had a poor prognosis than those with low-SYCP2 expression." (PMID 36159998, 2022). "The Kaplan–Meier survival curve indicated that patients suffering from breast carcinoma with high-SYCP2 mRNA expression had poor prognosis than those with low level of SYCP2 (p = 0.005)." (PMID 36159998, 2022). "The aim of this study was to elucidate the prognostic value and potential function of SYCP2 in breast carcinoma." (PMID 36159998, 2022). "Clinicopathologic characteristics of patients suffering from breast carcinoma with differential SYCP2 expression." (PMID 36159998, 2022). "In TCGA-BRCA, GSE45827, and GSE42568, the mRNA expression levels of SYCP2 in breast carcinoma tissues were significantly higher than that in normal tissues (p < 0.001)." (PMID 36159998, 2022). "First, the relationship between SYCP2 expression and the OS of overall patients suffering from breast carcinoma was investigated, instead of the relationship between SYCP2 expression and the OS of patients suffering from each subtype of breast carcinoma." (PMID 36159998, 2022). "Kaplan–Meier survival analysis showed that patients suffering from breast carcinoma characterized by high-SYCP2 expression had a poorer prognosis than patients with low-SYCP2 expression (p = 0.005)." (PMID 36159998, 2022).
breast carcinoma (continued). "Although the results of this study provided more insights into the relationship between SYCP2 and breast carcinoma, there are certain limitations that have to be mentioned." (PMID 36159998, 2022). "Second, the relationship between SYCP2 expression and the immune cells implicates the role of SYCP2 in the regulation tumor immunology in breast carcinoma." (PMID 36159998, 2022). "The results showed that SYCP2 expression was significantly elevated in breast carcinoma tissues as compared with that of normal tissues (p < 0.001)." (PMID 36159998, 2022). "Furthermore, our studies of two clinical cohorts find that SYCP2 overexpression correlates with breast cancer resistance to antibody-conjugated TOP1 inhibitor and ovarian cancer resistance to platinum treatment." (PMID 38383600, 2024). "Importantly, among the SYC family genes, SYCP2 is the only gene that showed significant upregulation in breast cancer compared to normal breast samples according to the TCGA database." (PMID 38383600, 2024). "Conclusively, SYCP2 plays a vital role in the pathogenesis and progression of human breast carcinoma, so it may serve as a promising prognostic molecular marker of poor survival." (PMID 36159998, 2022). "In brief, this study suggested that elevated SYCP2 expression has a prognostic value for individuals suffering from breast carcinoma and SYCP2 may act as a potential prognostic molecular marker of poor survival." (PMID 36159998, 2022). "Furthermore, a high level of SYCP2 expression was found to have a relationship to poor prognosis of breast carcinoma in the subgroups of T3, N0, and M0, and infiltrating ductal carcinoma (HR > 1, p < 0.05)." (PMID 36159998, 2022). "Lastly, the potential mechanisms of distinct SYCP2 in breast carcinoma were investigated." (PMID 36159998, 2022). "However, the potential role and relationship of SYCP2 suffering from breast carcinoma have been rarely characterized." (PMID 36159998, 2022). "Consequently, the results of this study revealed that SYCP2 has the potential to affect immune cell infiltration and interfere with immunotherapy, providing evidence for its use as a predictive biomarker for immunotherapy in patients with breast carcinoma." (PMID 36159998, 2022). "Importantly, SYCP2 was recently reported to be a biomarker for luminal A/B breast cancer." (PMID 33426787, 2021). "Our previous findings further indicate that breast cancer patients with elevated levels of SYCP2 exhibit increased resistance to DNA damage response (DDR) drug treatments, reinforcing SYCP2’s role as a key player in DDR-targeted therapy resistance." (PMID 40918650, 2025). "To further investigate if SYCP2 can function independently of BRCA1, we tested HCC1937 and HCC1954, two breast cancer cell lines defective for BRCA1." (PMID 38383600, 2024). "However, the specific mechanism of SYCP2 in breast carcinoma remains unclear." (PMID 36159998, 2022). "A recent study suggested that SYCP2 was significantly upregulated in luminal B tumors compared with the adjacent normal tissues, and the upregulated SYCP2 expression might serve as an independent indicator of shorter overall survival in luminal A/B breast carcinoma." (PMID 36159998, 2022). "Immunohistochemistry (IHC) analysis of breast cancer tissues and adjacent normal breast tissues from patients showed that SYCP2 protein was specifically detected in tumors but not in adjacent normal tissues." (PMID 38383600, 2024). "Overexpression of synaptonemal complex protein-2 (SYCP2) has been identified in various human papillomavirus (HPV)–related carcinomas, whereas its significant role in breast carcinoma remains unclear." (PMID 36159998, 2022). "Furthermore, SYCP2 mRNA levels are not significantly different in various subtypes of breast cancers." (PMID 38383600, 2024).
breast carcinoma (continued). "Thus, we speculated whether patients suffering from breast carcinoma are also accompanied by HPV infection, and whether SYCP2 might affect the prognosis of patients suffering from breast carcinoma by regulating keratinocyte differentiation, which needs further verification." (PMID 36159998, 2022). "However, SYCP2 expression remains unclear, and its prognostic value in breast carcinoma has not been confirmed." (PMID 36159998, 2022).
male infertility (7 papers, 2019 to 2025). The inability of the male to effect fertilization of an ovum after a specified period of unprotected intercourse. "These cases highlight a couple of observations about the gene–disease association between SYCP2 and male infertility and opportunities for future study." (PMID 39202451, 2024). "The reclassification improves SYCP2 variant interpretation and qualifies it for the inclusion on diagnostic male infertility gene panels and prioritization in whole exome or genome studies for related phenotypes." (PMID 39202451, 2024). "For this reason, while identifying the LOF variants in SYCP2 would be helpful in a diagnostic setting for male infertility, its utility in screening and predicting disease has yet to be established." (PMID 39202451, 2024). "The inclusion of these cases, along with the additional evidence from the literature, upgrades the strength of the gene–disease association for SYCP2 and male infertility from on the border of limited and moderate to strong." (PMID 39202451, 2024). "The upgraded classification provides sufficient clinical validity to improve SYCP2 variant interpretation and to qualify it for inclusion on diagnostic male infertility gene panels and prioritization in WES or WGS studies for related phenotypes." (PMID 39202451, 2024). "Despite substantial experimental evidence, the clinical validity of the gene–disease association between SYCP2 and male infertility had been classified as borderline limited to moderate previously due to insufficient case evidence." (PMID 39202451, 2024). "Of note, this study focuses on the relationship between the heterozygous LOF variants in SYCP2 and male infertility, thereby specifying the proposed mechanism of pathogenicity and mode of inheritance." (PMID 39202451, 2024). "When combined with the previous cases identified in the literature, six individuals with male infertility resulting from a low sperm count have been found to have heterozygous LOF variants in SYCP2." (PMID 39202451, 2024). "In existing studies, SYCP2 was reported as a robust candidate gene for male infertility since its encoding protein can interact directly with protein products of the male infertility genes TEX11 and SYCP3 in mice." (PMID 36159998, 2022). "SYCP2 was recently associated with male infertility, and it is thus unlikely that this patient’s TRIM71 variant alone is responsible for his cryptozoospermia, but an oligogenic cause of his phenotype cannot be ruled out." (PMID 34055789, 2021). "In addition, Sycp2-mediated pathogenicity has been shown to cause male infertility but only female subfertility in a mouse model." (PMID 39202451, 2024). "Furthermore, translocation-mediated SYCP2 overexpression has been suggested to cause male infertility." (PMID 35342360, 2022). "In conclusion, in this article, we describe a proband with male infertility harboring a novel splicing variation, c.2600 + 5G>C (p.Lys845*), in SYCP2 gene." (PMID 40432880, 2025). "Substantial experimental evidence supports the role of SYCP2 in male infertility, reinforcing the strong clinical validity of the classification of SYCP2 as a gene associated with autosomal dominant male infertility." (PMID 40432880, 2025). "The three cases identified in this study prompted a re-evaluation of the gene–disease relationship between SYCP2 and male infertility, which involved an investigation of the strength of both the genetic and experimental evidence." (PMID 39202451, 2024). "Nevertheless, recent research provided further evidence of SYCP2-mediated male infertility, and reported that SYCP2 translocation-mediated dysregulation and frameshift variants can result in human male infertility." (PMID 36159998, 2022). "Our results suggested that the c.2600+5G>C variation in SYCP2 might be the genetic etiology for male infertility in this pedigree." (PMID 40432880, 2025). "There is substantial experimental evidence supporting a role for SYCP2 in male infertility." (PMID 39202451, 2024).
male infertility (continued). "Additionally, the coiled-coil domain of murine SYCP2 interacts with SYCP3 and TEX11, which are themselves implicated in human male infertility." (PMID 39202451, 2024). "First, the variant spectrum of SYCP2-mediated male infertility has not yet been fully elucidated." (PMID 39202451, 2024). "It is also important to note that the relationship between SYCP2 and male infertility does not extend to female infertility." (PMID 39202451, 2024). "In addition, disruption of Sycp2 gene has been shown to cause male infertility, but only female infertility in mouse model, suggesting that the relationship between SYCP2 and male infertility does not extend to female infertility." (PMID 40432880, 2025).
cervical carcinoma (6 papers, 2013 to 2024). A carcinoma arising from either the exocervical squamous epithelium or the endocervical glandular epithelium. "As indicated by existing studies, SYCP2 belonging to the mitosis pathway is likely to play a certain role in the oncogenesis of cervical carcinoma and can be used as a diagnostic marker and therapeutic target; SYCP2 with alternative spliced events is likely to facilitate the CSCC progression." (PMID 36159998, 2022). "Of the top 10 ranked upregulated genes, 2 have not been previously reported as associated with cervical cancer (NUSAP1, and CDKN3), while the other 8 have been associated with cervical cancer either scantly (SYCP2, PRC1, CCNB2 and CDC20) or widely (MKI67, CDKN2A, CDC2, and PCNA)." (PMID 23405241, 2013). "PRC1, CCNB2, and SYCP2 are markers exclusively associated with invasive cervical cancer." (PMID 23405241, 2013). "During the progression of cervical cancer, SYCP2 was confirmed to be upregulated from normal cervical tissues, cervical intraepithelial neoplasia, to squamous cell carcinoma." (PMID 36159998, 2022). "SYCP2 is differentially expressed in 11 cancers and shows much stronger RNA‐Seq signals in breast and cervical cancer as compared to normal controls, which is coherent with the GeneChip data." (PMID 33426787, 2021). "SYCP2 was found to be one of the six most differentially expressed genes in HPV-positive cervical cancer compared to cervical epithelium control tissues and exhibits increasing expression levels in the progression from normal tissue to pre-cancerous lesions to cervical cancer." (PMID 34830845, 2021). "Finally, the SEHET class gene synaptonemal complex protein 2 (SYCP2) shows a particularly striking CT gene pattern because it is derepressed in a variety of somatic tumors, especially breast and cervical cancer to an unusually high level." (PMID 33426787, 2021). "In this work we identified 6 genes (PRC1, CCNB2, SYCP2 CDKN3, NUSAP1, and CDC20) associated with invasive cervical cancer that could be used either as markers for diagnosis or as therapeutic targets." (PMID 23405241, 2013). "The cervical cancer cell line HeLa and osteosarcoma cell line U2OS are widely used in the studies of DSB repair, and both these cancer cell lines express SYCP2." (PMID 38383600, 2024). "During the progression of cervical cancer, from normal cervical tissues to CIN 1, 2 and 3, the up‐regulated genes we confirmed were SYCP2, NEFH, CDKN2A and KRT17." (PMID 33624385, 2021).